OR1M1 (olfactory receptor family 1 subfamily M member 1)
Description:
Odorant receptor.
Synonyms: OR19-6; OR19-5
Tractability: Small molecule: it belongs to a druggable protein family. Antibody: UniProt places it where antibodies can reach, with high confidence; UniProt predicts a signal peptide or a membrane-spanning region; its Gene Ontology location is reachable by antibodies, with medium confidence.
Gene: Protein-coding gene on chromosome 19 (9,087,061 to 9,095,669, forward strand). Ensembl gene ENSG00000170929.
Subcellular location: Cell membrane
Pathways (Reactome):
Sensory Perception: Expression and translocation of olfactory receptors
Gene Ontology:
Molecular function: olfactory receptor activity; G protein-coupled receptor activity; signaling receptor activity
Biological process: signal transduction; detection of chemical stimulus involved in sensory perception of smell; G protein-coupled receptor signaling pathway; sensory perception of chemical stimulus
Cellular component: plasma membrane; membrane
Genetic constraint (gnomAD): Loss-of-function variants: 0 observed, 0.3 expected, observed/expected ratio (o/e) 0, 90% interval 0 to 1.87. That is too few expected variants to judge how well the gene tolerates losing a copy. Missense variants: 397 observed, 416.28 expected, observed/expected ratio (o/e) 0.95, 90% interval 0.88 to 1.04. Synonymous variants: 157 observed, 171.05 expected, observed/expected ratio (o/e) 0.92, 90% interval 0.81 to 1.05.
Homologues: Orthologues: macaque OR1M1 (94% identical), dog OR1M1B (88% identical), rat Or1m1 (86% identical), mouse Or1m1 (85% identical), guinea pig OR1M1 (85% identical), rabbit OR1M1 (82% identical). Paralogues in human: OR7D2 (57% identical), OR1F1 (55% identical), OR1E1 (54% identical), OR1N1 (54% identical), OR1G1 (54% identical), OR1J1 (54% identical), OR1J2 (54% identical), OR7D4 (54% identical), OR1E2 (54% identical), OR1J4 (54% identical), OR1I1 (53% identical), OR7A17 (53% identical), and 116 more.